SYP (synaptophysin)
Diseases named in the same sentence as SYP in open-access papers (continued):
Sharing a sentence is not in itself a finding about the gene and the disease.
tumor (663 papers, 2004 to 2026). "Immunohistologically, the tumor cells were positive for the neuroendocrine markers synaptophysin and insulinoma-associated protein 1 (INSM1) and demonstrated an antigen Kiel 67 (Ki-67) proliferation rate of 100%." (PMID 41333490, 2025). "Patchy staining for neuroendocrine markers such as INSM1 and synaptophysin can present a diagnostic pitfall, particularly when a tumor exhibits a monotonous epithelioid morphology with vesicular chromatin." (PMID 39404971, 2024). "Tumor cells were diffusely positive for Synaptophysin, CD56, INI1 and SMARCA4 associated with negativity for GFAP, OLIG-2, EMA, BCOR, LIN28A and MIC-2." (PMID 36934287, 2023). "It is noteworthy that both tumor types can focally express neuroendocrine markers (synaptophysin, chromogranin, and INSM1) in most SMARCA4-deficient carcinomas and up to 18% of SMARCB1-deficient carcinomas." (PMID 36941503, 2023). "Tumor cells were diffusely positive for Synaptophysin, CD56, INI1, SMARCA4 and ATRX associated with negativity for GFAP, OLIG-2, EMA, BCOR, LIN28A, EZHIP, MIC-2, Cytokeratin’s, SMA, Desmin and Myogenin." (PMID 36934287, 2023). "In this process, the pathologist can analyze if the tumor cells express Chromogranin A and Synaptophysin, two proteins associated with the regulation of secretory vesicles." (PMID 34571751, 2021). "As pSyn was significantly associated with tumor progression and metastasis, platelet-expressed synaptophysin shows great potential as a novel, dynamic biomarker in neuroendocrine malignancies." (PMID 34064565, 2021). "The tumor cells were positive for cytokeratin and neuroendocrine markers including chromogranin, synaptophysin, and NSE, diagnostic of gastric carcinoid." (PMID 23401809, 2013). "We therefore asked whether Pten loss (increased mTOR signaling) rescues the post-mitotic tumor cells from death by staining for SYP or NeuN and TUNEL." (PMID 40766638, 2025). "Two board-certified pathologists (A.P., M.T.)confirmed PD tumoroids were alike the original tumor tissue in high tumor content, in tumor cell morphology, and in the expression of diagnostic neuroendocrine biomarker synaptophysin, based on the cytology of micro-cell-blocks from cultured cells." (PMID 38429350, 2024). "However, development of resistance inevitably occurs and this is associated with tumour differentiation to more aggressive forms such as a neuroendocrine phenotype characterized by expression of neuron specific enolase and synaptophysin." (PMID 32802517, 2020). "Immunohistochemistry (IHC) should be conducted for all suspected cases of NETs with a minimal panel of markers (low-weight cytokeratin, synaptophysin and chromogranin A) to confirm the neuroendocrine nature of the tumour [IVA], and reduce the chance of diagnostic errors." (PMID 28194228, 2017). "Therewas no synaptophysin expression in the desmoplastic areas, but at the edge with normalbrain synaptophysin highlighted intermingling of tumor and normal neuropil." (PMID 41522855, 2026). "To facilitate mechanistic and pharmacologic studies, we established NCI-LYM-1, a patient-derived organoid/PDX from an AR-negative, ASCL1+/SYP+ lymph node metastasis, which faithfully recapitulates the donor tumor’s molecular and phenotypic features." (PMID 41542660, 2026). "Without any prior selection for chromaffin tumour cells, passaged cultures were obtained with over 80% synaptophysin-expressing chromaffin tumour cells, suggesting that this highly promising strategy deserves further exploration." (PMID 41881005, 2026). "The biopsy of the breast revealed small cell neuroendocrine carcinoma with the similar morphology to the primary tumor, with positive synaptophysin, and weak NSE." (PMID 41589095, 2026). "Peritoneum biopsy revealed plasmacytoid tumor cells which were positive for calcitonin and synaptophysin staining." (PMID 41977034, 2026).
tumor (continued). "Glial fibrillary acidic protein (GFAP) is observed in the glial component of the tumours and synaptophysin is seen in the neuronal or ganglion cell components." (PMID 40013208, 2025). "Chromogranin A and synaptophysin are markers of neuroendocrine differentiation, confirming the tumor’s neuroendocrine origin." (PMID 41467146, 2025). "Immunohistochemical staining for chromogranin A (CgA) and synaptophysin was performed in all tumor tissue samples, and both markers were positive in all cases." (PMID 41427045, 2025). "NED by immunohistochemistry typically presents as scattered non‐diffuse staining for neuroendocrine markers such as synaptophysin or chromogranin in a tumour that would otherwise be considered a conventional adenocarcinoma." (PMID 39526928, 2025). "Tumor cells expressed 2 or more neuroendocrine markers: synaptophysin (SYN) 100 % (4/4), CD56 100 % (4/4), and chromogranin A (CgA) 50 % (2/4)." (PMID 41305788, 2025). "Sellar tumor samples were consistently immunoreactive for neuroendocrine markers chromogranin A, synaptophysin, CD56/NCAM, and S100, further supporting a pituitary NET classification." (PMID 41203869, 2025). "Synaptophysin staining exhibited substantial variability, both between organoids from different tumors and among organoids derived from the same tumor." (PMID 40576438, 2025). "This review explores the diagnostic value of immunohistochemical surrogate markers, vimentin, synaptophysin, and histone H3 lysine 27 methylation (H3K27me), in distinguishing these tumor types." (PMID 40937216, 2025). "The tumor was evaluated with immunohistochemical stains and found to be positive for synaptophysin, Lu-5, and CDX-2." (PMID 41458666, 2025). "All samples were stained with H&E, and immunostained with the neuroendocrine tissue marker synaptophysin to confirm that the tumours were NETs." (PMID 39579056, 2025). "The tumour cells were positive for synaptophysin GATA‐3, focally positive for chromogranin, while negative for calretinin, CA9, BerEP4 and cytokeratin AE1/AE3." (PMID 40588841, 2025). "CD3+ T cells, CD20+ B lymphocytes, CD68+ macrophages, CD66b+ neutrophils, the nucleus-defining dye DAPI, and tumor cells expressing CD56 and synaptophysin (tumor markers: TM) were stained by multi-parametric fluorescence IHC together in one tissue section." (PMID 40282480, 2025). "Immunohistochemistry (IHC) revealed that the tumor cells were strongly and diffusely positive for synaptophysin favoring PB." (PMID 40224232, 2025). "We also detected nerve fibres immunoreactive for neurofilaments and SYP at the border or in the vicinity of human SCLC tumours." (PMID 40931078, 2025). "Synaptophysin, a critical marker of synaptic density, has also been observed to increase in peri-tumoural regions." (PMID 40806177, 2025). "Immunohistochemistry demonstrated that the tumor cells were positive for chromogranin A, synaptophysin, and CD56." (PMID 40091949, 2025). "Immunohistochemical analysis of the tumor section demonstrated strongly positive staining for chromogranin A (CgA), synaptophysin, and a Ki-67 proliferation index ranging from 3% to 20%, leading to the final diagnosis of a SBNET." (PMID 40324239, 2025). "On the other hand, immunohistochemical analysis of the initial TURP specimen revealed relatively high expression of synaptophysin in a subset of tumor cells, indicating neuroendocrine differentiation within part of the tumor." (PMID 40692870, 2025). "Based on all this information, the histopathology was revisited, additional immunochemical stains were performed, and the tumor was found to be positive for synaptophysin and neuron-specific enolase." (PMID 40270995, 2025). "Diagnosis is confirmed by microscopic observation of the morphological features of the tumor cells and detection of the expression of neuroendocrine markers, such as synaptophysin (Syn), chromogranin (CgA), and CD56." (PMID 40248205, 2025).
tumor (continued). "This was consistent with the results of histological staining, which identified a PSA-negative tumor with expression of the NE marker synaptophysin." (PMID 40181402, 2025). "As a result, for samples PanNET1, PanNET3, and PanNET4, segmentation to acquire tumor and islet cell AOIs was performed based on synaptophysin immunofluorescence signal." (PMID 39245631, 2025). "Primary tumor cells were isolated, cultured, and characterized using Phox2b and synaptophysin staining." (PMID 40552293, 2025). "By IHC, the tumor demonstrated diffuse positivity to synaptophysin, PLAP negativity, retained INI-1, focally retained ATRX expression, and focally retained nuclear expression of SMARCA4." (PMID 41353556, 2025). "A subsequent lung biopsy revealed synaptophysin-positive SCLC harboring the same EGFR exon 19 deletion (L747-P753insQ) as the original tumor." (PMID 41516316, 2025). "The tumour cells and processes had diffuse synaptophysin positivity, and ganglion cells were GFAP positive, suggestive of an anaplastic ganglioglioma." (PMID 40013208, 2025). "Representative full‐face sections of tumour were stained for synaptophysin, chromogranin‐A and serotonin by immunohistochemistry, and staining results were correlated with disease‐free survival (DFS) and overall survival (OS)." (PMID 39526928, 2025). "In an orthotopic NEPC murine model, NO treatment led to a substantial reduction in tumor burden and metastasis to the liver and brain, with corresponding decreases in chromogranin and synaptophysin expression." (PMID 41198652, 2025). "Immunohistochemical staining supported the diagnosis: tumor cells were positive for chromogranin A, synaptophysin, and S-100." (PMID 41467146, 2025). "Immunohistochemical analysis demonstrated that the majority of tumor cells expressed synaptophysin, confirming neuroendocrine differentiation." (PMID 40909459, 2025). "Again, the tumor stained positive for synaptophysin, chromogranin, and CD56, with less than 2% Ki-67 positive." (PMID 39974256, 2025). "Conversely, larger tumours mostly lacked intralesional nerve fibres and, when present, GAP43- and synaptophysin (SYP)-positive fibres were observed at the tumour border." (PMID 40931078, 2025). "Univariate analysis did not reveal a statistically significant association between mDFS and age, gender, smoking history, tumor localization, TTF-1, chromogranin A, synaptophysin, CD56, adjuvant radiotherapy, or type of surgery." (PMID 41153253, 2025). "These neoplasms often show a characteristic morphology and express general markers of neuroendocrine differentiation, such as synaptophysin and chromogranin." (PMID 40730596, 2025). "The tumor from our patient demonstrated coexpression of epithelial markers AE1/AE3 as well as neuroendocrine markers including synaptophysin, chromogranin A, INSM1, and CD56." (PMID 40843719, 2025). "This makes synaptophysin a suitable marker for monitoring the course of tumours and the response to treatment in patients with NETs." (PMID 39036213, 2024). "Histopathological examination and immunohistochemical staining using neuroendocrine markers (chromogranin, synaptophysin, S-100 protein, and CD-56) later confirmed the tumor as a retroperitoneal paraganglioma." (PMID 39703846, 2024). "In two further cases, a combined SCC with LCNEC was diagnosed, using only synaptophysin staining for the confirmation of neuroendocrine differentiation in the second tumor component." (PMID 39335769, 2024). "Immunohistochemistry performed as part of the diagnostic work up on the nodal tumour showed positive staining for androgen receptor (AR), NKX3.1, PSA polyclonal, and Synaptophysin." (PMID 38374116, 2024). "Histologically, tumors from both intact and castrated mice exhibited KRT8+NKX3.1+ luminal-like regions along with SYP+INSM1+ NE tumor foci." (PMID 39024561, 2024). "The immunohistochemical results showed that the tumor cells were diffuse and positive for chromogranin A (CgA), synaptophysin (Syn), and INSM1." (PMID 39518315, 2024).
tumor (continued). "At immunohistochemistry (IHC), tumor cells are positive for keratin, neuroendocrine markers including synaptophysin and chromogranin-A, and glucagon." (PMID 39331358, 2024). "We implemented in situ hybridization to detect messenger ribonucleic acid (mRNA) transcripts of CXCL9, CXCL10, and IL-8 along with a synaptophysin immunohistochemical co-stain to identify tumor cells." (PMID 38822345, 2024). "Last, we performed immunohistochemistry validation on PDX tumor tissue (n = 5) and confirmed in situ expression of the neuronal marker synaptophysin (SYP), which correlated with fraction of neuronal cells detected in our single-cell meta-analysis." (PMID 39060228, 2024). "Despite this variation for GFAP and synaptophysin staining, desmin was positive in a significant percentage of neoplastic cells throughout the neoplasm, with rare cells showing densely eosinophilic cytoplasm or elongation." (PMID 39228008, 2024). "All 12 primary tumours were immunohistochemically positive for chromogranin A, synaptophysin, and their respective secreted hormones." (PMID 39122816, 2024). "Immunohistochemical analysis showed tumor cells positive for pan-endocrine markers (synaptophysin, CD56, INSM1 and chromogranin)." (PMID 38678248, 2024). "On immunohistochemistry (IHC), the tumor cells showed diffuse positivity for S100 and weak positivity for synaptophysin." (PMID 39493091, 2024). "All neoplasms were investigated with immunohistochemistry for neuroendocrine markers (Synaptophysin, Chromogranin-A), ATRX, DAXX, ARX, and PDX1 transcription factors." (PMID 39331358, 2024). "In case #5 neurofilament and synaptophysin staining suggested both areas of infiltration and a component of neural antigen expression within the tumor." (PMID 39228008, 2024). "The tumor's stage was found to be pTa4a, pN0, pMX, and the tumor immunohistochemical staining was positive for chromogranin, synaptophysin, pan-cytokeratin, and D2-40 all of which support the diagnosis of carcinoid tumor." (PMID 39100025, 2024). "Utilizing a mxIF panel of CD4, CD8, FOXP3, PD-1, Ki-67, and synaptophysin; T cells were appreciated throughout the tumor microenvironment of ONB." (PMID 38822345, 2024). "In the case under review, tumor cells exhibited strong positivity for synaptophysin, with abundant membrane-bound electron-dense neurosecretory granules." (PMID 39429475, 2024). "In all specimens, CHGA, SSTR2, and SYP exhibited strong staining in the (ductal) epithelial tumor cells." (PMID 39682758, 2024). "The primary T14 tumor cells were also strongly positive for the RB markers synaptophysin and TFF1 as well as for vimentin." (PMID 39695086, 2024). "Despite this variability, the observed synaptophysin expression highlights its potential utility as a supportive marker for this tumor." (PMID 39765541, 2024). "Focal positivity for chromogranin A (CgA) and synaptophysin (Syn) was observed in the tumor cells of GCA." (PMID 38500658, 2024). "DPYSL5, NCAM, CGA, SYP and AR protein expressions were evaluated in the tumor tissue samples using immunohistochemistry (IHC)." (PMID 38238517, 2024). "ONB is usually diffusely positive for chromogranin and synaptophysin, with S100 protein-positive sustentacular cells characteristically highlighting the periphery of tumor lobules." (PMID 38315310, 2024). "Since, on IHC, the tumor cells showed positivity for S100 and weak positivity for synaptophysin, we went ahead with molecular FISH analysis." (PMID 39493091, 2024). "Strong and diffuse expression of synaptophysin in tumor cells, S100 expression in sustentacular cells at the periphery of nests, and lack of pancytokeratin expression supported the diagnosis of PGL." (PMID 37503488, 2023). "Immunohistochemistry revealed that the tumor cells diffusely and strongly expressed cytokeratin, synaptophysin, chromogranin A, GATA3, CAM5.2, and estrogen and progesterone receptors; partially expressed AR and GCDFP15." (PMID 38115331, 2023).
tumor (continued). "After H and E staining and immunohistochemical staining, some tumor cells showed typical positive synaptophysin (Syn) and Chromogranin (CgA) staining." (PMID 36836889, 2023). "Histological examinations of the resected specimen from the both sites showed the same findings, as a high nucleus-to-cytoplasm ratio in the tumor cells, as well as immunohistochemically positive findings for chromogranin A, synaptophysin, and AFP." (PMID 37721573, 2023). "HE staining, in conjunction with nestin and synaptophysin staining, was carried out to assess the extent of the tumor mass." (PMID 36993983, 2023). "By immunohistochemistry, the tumor cells showed retained INI-1 expression, focal CD10 expression, and loss of BRG1, CK-pan, synaptophysin, desmin, and ER expression." (PMID 37194064, 2023). "The histologic diagnosis of the tumor was confirmed by the positive immunohistochemical staining for pan-cytokeratin, synaptophysin, and Ki-67." (PMID 37543794, 2023). "Immunohistochemical findings showed the tumor cells were positive for chromogranin A, synaptophysin, and CD56." (PMID 37031336, 2023). "Tumor cells express both epithelial and neuroendocrine markers including CgA, synaptophysin, NSE, CD57, CD56, PGP9.5 and ‘dot-like’ cytokeratins." (PMID 38137784, 2023). "Immunohistochemistry showed that the tumor cells diffusely and strongly expressed cytokeratin, synaptophysin, chromogranin A, GATA3, and CAM5.2." (PMID 38115331, 2023). "The immunobiological study of the tumour markers typically demonstrates positivity of neuron-specific enolase (74.1–90%), CgA (66.7–95%), and synaptophysin (48.9–91.7%) and CD56 and cytokeratin." (PMID 37386646, 2023). "The tumor cells were strongly positive for CgA and synaptophysin, with a Ki67 labeling index of 3.0%." (PMID 37867522, 2023). "Immunohistochemistry revealed a diffuse positivity for synaptophysin with a weak or moderate cytoplasmic reactivity, while the tumor cell matrix showed a consistently strong staining." (PMID 36933012, 2023). "Clinically, high levels of neural synaptic transcripts (SYP and SNAP25) are associated with inferior prognosis and advanced tumor stage in pan-cancer TCGA tumors, indicating a tumor promoting role of TME neural signals." (PMID 37463926, 2023). "In terms of immunophenotype, the tumor tissues express chromogranin A (CgA), synaptophysin (Syn), and CD56." (PMID 37724114, 2023). "She then underwent spleen-preserving distal pancreatectomy; a 10-mm tumor positive for chromogranin A, synaptophysin and insulin was identified." (PMID 37563593, 2023). "Histology shows ganglionic neuronal tumour cells, which express synaptophysin and/or Chromogranin A and which can be binucleated by contrast with residual normal neurons." (PMID 36831464, 2023). "The demonstration of the neuroendocrine nature of the tumor requires the identification of one or more neuroendocrine markers (synaptophysin, chromogranin A, CD56, or INSM1) in at least 10% of tumor cells." (PMID 36836564, 2023). "At tumor resection following induction chemotherapy, tumor cells stained positive for chromogranin A and synaptophysin and focal ganglion cells, suggestive of neuroblastoma." (PMID 37664065, 2023). "Immunohistochemical investigations revealed that tumor cells were positive for chromogranin A, synaptophysin, and CD56." (PMID 37031336, 2023). "Immunohistochemical staining also revealed that the tumor was positive for chromogranin A, synaptophysin, and CD56." (PMID 35754064, 2022). "Chromogranin A (CgA), Synaptophysin and neuron-specific enolase (NSE) are widely used in clinical routines as diagnostic tumor markers." (PMID 35326628, 2022).